MALAT1 (metastasis associated lung adenocarcinoma transcript 1)
Diseases named in the same sentence as MALAT1 in open-access papers (continued):
Sharing a sentence is not in itself a finding about the gene and the disease.
cancer (continued). "The growing body of evidence revealed the significant role of MALAT-1 in cancer pathophysiology, including cancer cell growth, metastasis, and invasion." (PMID 38511067, 2024). "MALAT-1 competitively binds to miR-125a-3p and activates FoxM1, inducing cancer proliferation and invasion." (PMID 38201661, 2024). "The lncRNA MALAT1 is located at chromosomal region 11q13.1 in humans and is involved in multiple physiopathological processes, including cancer and diabetic complications." (PMID 38439031, 2024). "MALAT1 is another long non-coding RNA (lncRNA) that has been widely reported as differentially expressed in cancer." (PMID 38612643, 2024). "Subsequently, overexpression of MALAT1 was also found to be involved in tumor cell proliferation, migration, invasion and apoptosis in various cancers." (PMID 38517388, 2024). "Controversial reports exist between in vitro and in vivo studies regarding Malat1’s function in nuclear speckles and cancers 17–21,54–57." (PMID 38234849, 2024). "Cumulatively, MALAT1 appears to assume a pivotal role in driving EMT processes across various cancer types." (PMID 39323624, 2024). "Recent research has demonstrated that MALAT1 is also overexpressed in various types of human cancer, such as those that affect the breast, pancreatic, colon, prostate, and liver." (PMID 39512820, 2024). "In our study, we observed significant overexpression of MALAT1 in the 5-FU-resistant sub-cell line compared to its parental cells, consistent with findings in different types of cancer." (PMID 39246994, 2024). "MALAT1 has demonstrated involvement in promoting cell proliferation and survival across diverse cancer types." (PMID 39323624, 2024). "MALAT1 was found to decrease autophagic flux and increase IL-6 by regulating the PTEN/AKT/mTOR and SQSTM1/NF-κB, thereby transforming fibroblasts into cancer-associated fibroblasts to accelerate GC development." (PMID 37588204, 2024). "The lncRNA known as MALAT1 has been well recognized as a pivotal contributor to the progression of cancer." (PMID 39346921, 2024). "Despite its ubiquitous expression, strong conservation, and high abundance in all mammalian cells, both the normal and the cancer functions of Malat1 have remained a mystery." (PMID 39195572, 2024). "A short 16-mer ASO gapmer with phosphorothioate-modified S-2′-O-ethylene-2′,4′-bridged nucleic acid targeted MALAT1 in an MMTV-PyMT carcinoma model, rendering slower tumor growth and reduced metastasis." (PMID 38338910, 2024). "In cancer cells, the long non-coding RNA (lncRNA) MALAT1 has arisen as a key partner for the Polycomb Repressive Complex 2 (PRC2), an epigenetic modifier." (PMID 37367050, 2023). "MALAT1 affects theinitiation and progression of tumors of various localizations, includinglaryngeal cancer, cancer of the laryngopharynx, as well as thyroid, esophageal,lung, liver, and ovarian cancers." (PMID 37538803, 2023). "Previous studies have shown that MALAT1 is aberrantly expressed in numerous cancers and contributes to tumor malignant progression." (PMID 36813772, 2023). "All these cancer types share two main features: (i) MALAT1 was reported to have direct regulatory functions on the MAPK pathway and (ii) MALAT1 inhibition caused disadvantageous reactions in the respective cancer cells." (PMID 37235843, 2023). "MALAT1 long non-coding RNA accumulates in the nucleus, where it plays a crucialrole in cancer progression and the formation of nuclear paraspeckles." (PMID 37538803, 2023). "While MALAT1 is highly conserved among species and widely expressed in normal tissues, it is overexpressed in several cancers and its expression correlates with poor overall patient survival." (PMID 36649031, 2023). "It was also shown that the expression of MALAT1 is correlated to tumor size, the state of lymph node metastasis, as well as the staging of cancer." (PMID 36934373, 2023).
cancer (continued). "Our findings demonstrate new insights into MALAT1-mediated MAPK-pathway gene regulation and a paradigm of MALAT1 expression in MAPK-signaling-dependent cancer types." (PMID 37235843, 2023). "Again, MALAT-1 contributes to the development of different types of cancer through interaction with Serine/Arginine splicing factors and changing their distribution to nuclear speckle domains." (PMID 37888204, 2023). "A notable example is MALAT1 with an unusual up-regulation in cancer cells serving as a robust biomarker for several types of cancer including in breast and lung tissue." (PMID 37991492, 2023). "MALAT1 was a well-known lncRNA, which can function as a ceRNA by sponging to miRNAs to indirectly regulate targeted mRNAs in various cancers." (PMID 37960753, 2023). "MALAT1-targeting ASO nanostructures have shown promising potential for the treatment of cancer metastasis in vivo." (PMID 37235843, 2023). "In the Tin list, this concerns the genes BDNF Antisense RNA (BDNF-AS), Biotinidase (BTD), Metastasis-Associated Lung Adenocarcinoma Transcript 1 (MALAT1), MicroRNA 210 (MIR210), and Prostate Cancer-Associated Transcript 1 (PCAT1)." (PMID 37736859, 2023). "MALAT1 is a lncRNA involved in various biological processes and can influence the onset and progression of several malignant cancers, including HNSCC." (PMID 37733767, 2023). "As for PRC2, MALAT1 overexpression has been proposed as a cancer biomarker, and it currently represents a promising therapeutic target to treat tumor progression." (PMID 37367050, 2023). "Through various mechanisms, dysregulated MALAT1 expression affects all kinds of human cancers as an oncogene or tumor suppressor, acting upon cellular processes such as alternative splicing, epithelial to mesenchymal transition (EMT), apoptosis, and autophagy." (PMID 37444543, 2023). "There is a long list of reports supporting that MALAT1 promotes cell proliferation at least within the context of cancer cells." (PMID 36869729, 2023). "Wound healing and Transwell invasion assays were performed to assess the effects of MALAT1 on cell motility, a characteristic of cancer cells." (PMID 37667226, 2023). "Together, these findings suggest that the MAPK-signaling/MALAT1 axis has essential and tissue-specific oncogenic roles in cancer." (PMID 37235843, 2023). "Later, it was reported that MALAT1 promotes the progression of TNBC by inhibition of apoptosis of cancer cells along with stimulating metastasis followed by cell proliferation." (PMID 37795578, 2023). "First, in the context of cancer metastasis, MALAT1 appears to instigate epithelial-to-mesenchymal transition (EMT) and enhance the metastatic potential of cancer cells through modulation of the EZH2-Notch1 signaling pathway." (PMID 38203269, 2023). "MALAT1 was confirmed to participate in the progression of cancers through the regulatory expression of miRNAs." (PMID 36700118, 2023). "Malat1 was first identified as highly expressed in both malignant tumors and healthy lung and pancreas with high interspecies conservation." (PMID 38127070, 2023). "Another research group reported that inhibition of MALAT1 had also been found to alter apoptosis through the IKKα/NF-κB pathway, thereby boosting the sensitivity of cancer cells to 5-FU in HCC." (PMID 36829256, 2023). "In recent years, MALAT1, the “star molecule” of lncRNAs, has been comprehensively studied, and its mechanism of action in various cancers has been clarified." (PMID 36903369, 2023). "Overexpression of miR-20b attenuates the proportion of cancer stem cells via the direct targeting of Oct4 and MALAT1, critical positive regulators of cancer stem cell stemness, and finally eases tumor regression." (PMID 36717861, 2023). "In recent years, more and more studies have found that MALAT1 was strongly related to the regulation of autophagy in cancer cells." (PMID 36829256, 2023). "In this review, we discussed the functions and mechanisms of MALAT1 in cancer chemotherapy resistance." (PMID 36829256, 2023).
cancer (continued). "We set up a high-content-imaging-based HTS (high-throughput screening)-compatible fluorescence in situ hybridization assay to identify novel small molecules that modulate MALAT1 lncRNA levels in cancer cells." (PMID 36649031, 2023). "We are currently conducting ChIP- and CHART-seq experiments in other human cancers where MALAT1 expression should be higher." (PMID 37367050, 2023). "MALAT1 is widely expressed in mammalian normal tissues and abnormally expressed in many human malignant tumors, which alters the biological phenotype of tumor cells." (PMID 38006062, 2023). "The long non-coding RNA MALAT1 is upregulated in a variety of cancers and can be detected in the nucleus of many cancer cells by fluorescent RNA in situ hybridization." (PMID 36649031, 2023). "Further research is needed to fully elucidate the molecular mechanisms by which MALAT-1 exerts its functional roles in cancer cells." (PMID 38124072, 2023). "MALAT1 depletion induces metabolic reprogramming of cancer cells toward a more glycolytic phenotype." (PMID 36674430, 2023). "Since choline synthesis is a crucial event for cancer cells, MALAT1 targeting downregulates CHKA and CERK activity; this effect seems to overlap the activity of CHKA inhibitors." (PMID 36674430, 2023). "LncRNA MALAT1, one of the earliest lncRNAs to be described in the process of cancer metastasis, can affect cancer invasion and metastasis by regulating EMT." (PMID 36760471, 2023). "MALAT1 suppression reduced cancer cell growth, invasion, migration, and colony formation and elevated cell cycle arrest and apoptosis." (PMID 36831169, 2023). "Analysis of The Cancer Genome Atlas (TCGA) database revealed that MALAT1 was upregulated in many types of cancer tissues, including HCC, compared with normal tissues." (PMID 37653482, 2023). "In general, the high expression of MALAT1 regulates apoptosis-related genes and molecules, affects cancer cell apoptosis, and triggers cancer drug resistance." (PMID 36829256, 2023). "MALAT1 is a highly conserved long-noncoding RNA whose overexpression correlates with poor overall patient survival in some cancers." (PMID 36649031, 2023). "MALAT1 expression levels were notably higher in cancer tissues and positive lymph nodes compared with those of healthy controls (1.9 and 1.97 times higher than the controls, respectively, p < 0.05)." (PMID 38203269, 2023). "LncRNA MALAT1 is one of the best-studied lncRNAs in the pathogenesis of various diseases, including cancers and cardiovascular diseases." (PMID 37250901, 2023). "Several studies have addressed the feasibility of targeting MALAT1 in order toimprove the treatment of malignant neoplasms." (PMID 37538803, 2023). "For instance, MALAT1 regulates cancer cell proliferation, differentiation, metastasis and chemoresistance through various mechanisms, such as overexpression, translocation and amplifications." (PMID 36864364, 2023). "Like NEAT1, MALAT1 is upregulated in superclusters A and B compared to C. Its effects are manifold and some controversy exists about its activities in different cancer types and settings." (PMID 38066300, 2023). "MALAT1 can also contribute to cancer resistance to chemotherapeutic drugs by enhancing the stemness of cancer cells." (PMID 36829256, 2023). "Previous studies have shown that MALAT1 plays an important role as an oncogenic molecule in cancers." (PMID 37653482, 2023). "MALAT-1 influences the tumor microenvironment by modulating the communication between cancer cells and surrounding stromal cells." (PMID 38124072, 2023). "Extensively explored in various cancers MALAT1’s propensity for fostering hyperproliferation and metastasisis noteworthy." (PMID 37812599, 2023). "Most of these lncRNAs were tumor-specific, although NEAT1 and MALAT1 were identified in a pan-cancer context, confirming their role in tumorigenesis." (PMID 38068923, 2023).
cancer (continued). "To test this, we expanded the expression analysis of patient-derived tissue in other TCGA-listed types of cancer in which MALAT1 is known to have essential MAPK-signaling regulating functions." (PMID 37235843, 2023). "Studies have shown that MALAT1 can both facilitate and suppress cancer development and is common in various cancers." (PMID 38045858, 2023). "In non-cancer contexts, MALAT1 has been reported to activate cGAS/STING through CREB, therefore promoting inflammatory lung conditions." (PMID 37370745, 2023). "This study is the basis for the identification of novel targets that lead to a reduction of the oncogenic lncRNA MALAT1 in a cancer setting." (PMID 36649031, 2023). "Despite an increasing understanding of how MALAT1 upregulation contributes to cancer development and progression, less is known about its physiological functions in non-transformed cells." (PMID 36869729, 2023). "In summary, MALAT1 overexpression affects the autophagy of cancer cells and leads to drug resistance." (PMID 36829256, 2023). "To evaluate the effects of such MALAT1 fusions on cancer cell biology in the TRAMP mouse model, we knocked down MALAT1 expression in TRAMPC1 cells using lentiviral shRNA delivery." (PMID 35159020, 2022). "Accordingly, MALAT1 is particularly abundant in cancer cell lines arguing for a key role in carcinogenesis." (PMID 35456025, 2022). "In this regard, ANRASSF1, PCA3 (NCT01024959), HULC (DRKS00017517), CCAT1 (NCT04269746), H19 (NCT04767750), ANRIL, MALAT1 are currently in clinical trial (trial number given in brackets) for cancer patients." (PMID 36428681, 2022). "miR-124 was upregulated when MALAT1 was silenced and downregulation of miR-124 restored the cancer cell characteristics that would otherwise be seen in MALAT1 expressing cells." (PMID 36059695, 2022). "This guided us to perform experiments wherein we rescued cancer cell characteristics in MALAT1-silenced cells through targeted dysregulation of miR-124." (PMID 36059695, 2022). "MALAT-1 has been shown to play a role in tumorigenesis and cancer progression of castration resistant prostate cancer; on the other hand, its association with disease progression and survival in PCa patients is still unclear." (PMID 35016717, 2022). "The in vivo study further proved the functions of the MALAT1/MYBL2/mTOR axis in cancer proliferation and glucose metabolism in PCa cells." (PMID 35557985, 2022). "A recent study has shown that LncRNA MALAT-1-specific ASOs suppress cancer cell metastasis in vitro and in vivo." (PMID 35886037, 2022). "As one of the first lncRNAs discovered, metastasis-associated lung adenocarcinoma transcript 1 (MALAT1) has been linked to the pathophysiology of inflammatory illnesses, metabolic diseases, and cancer." (PMID 36354526, 2022). "Then, for the lncRNA-related PCGs, GO, and KEGG analyses were performed to show the potential roles of lncRNAs MALAT1 in cancer development." (PMID 36163080, 2022). "Recently, a numeral study has explored the fundamental role of MALAT1 in the development of drug resistance in different cancer cells." (PMID 35281907, 2022). "Subsequent mechanistic studies have demonstrated a vital function of MALAT1 in the development and progression of various cancers, including CRC." (PMID 35558512, 2022). "MALAT1 promotes cell proliferation and migration, and its depletion inhibits both in vitro cell motility and metastasis in mouse cancer models." (PMID 35016717, 2022). "In our experiments, we observed reduced levels of stem cells markers, both Sox2 and Nanog in CTCL cells, upon silencing of MALAT1, which is a clear indication that MALAT1 promotes cancer stem cell phenotype as silencing of MALAT1 reduces stem cell markers." (PMID 36059695, 2022). "hnRNPC has also been shown to be a modulator of many important oncogenic genes, including breast cancer susceptibility gene (BRCA), metastasis associated in lung denocarcinoma transcript 1 (MALAT1), and c-Myc." (PMID 35355828, 2022).
cancer (continued). "Initially identified as a cancer biomarker, MALAT1 has diverse roles in multiple different cancer types." (PMID 34791525, 2022). "The EMT induced by lncRNAs plays an important role in cancer metastasis and accordingly MALAT1-induced EMT has been reported to regulate cancer metastasis." (PMID 36059695, 2022). "For instance, MALAT1 knockdown through siRNA has been reported to block cancer cell proliferation and reduce tumour growth in NSCLC by downregulating COMMD8." (PMID 35379783, 2022). "MALAT1 is one such lncRNA that has now been extensively studied in various different cancers with hundreds of available reports on this lncRNA in the scientific literature." (PMID 36059695, 2022). "As a result, MALAT1 altered cancer cell proliferation, migration, invasion, and sensitivity to therapeutics." (PMID 35656022, 2022). "MALAT1 has been shown to contribute in a variety of functions in cancer cells such as, enhancement of EMT, acting as miRNA sponges, and stimulating autophagic events." (PMID 35281907, 2022). "MALAT1 is a highly expressed lncRNA that regulates numerous physiological and pathological processes in many tissues, including myogenesis, cancer, aneurysms, etc.." (PMID 35806493, 2022). "Previous studies have revealed that MALAT1 is commonly upregulated in human cancer tissues of diverse organ origins and that MALAT1 induces proliferation, migration and invasion of cancer cells in vitro and tumor metastasis in mice." (PMID 35558512, 2022). "The status of lncRNA MALAT1 in CTCL patients is not clear and moreover there is quite some controversy regarding the oncogenic vs tumor suppressive role of MALAT1 in different cancers." (PMID 36059695, 2022). "According to studies, MALAT1 was identified as one of the primary lncRNAs, in cancer and a cancer biomarker." (PMID 36163080, 2022). "MALAT1 is an oncogene with high conservation degree, which promotes cancer development and regulates radio-sensitivity and chemo-sensitivity in cancer cells." (PMID 35609308, 2022). "In vascular endothelial and cancer cells, MALAT1 expression triggers various changes such as proinflammatory cytokine expression, cancer cell proliferation and metastasis, and increased endothelial cell permeability." (PMID 36419933, 2022). "MALAT1 was able to control cancer cell EMT, migration, invasion, and metastasis by orchestrating the Wnt signaling." (PMID 35656022, 2022). "We found that MALAT1 expression in cancer tissues is significantly higher than in normal tissues (P = 0.001)." (PMID 35016717, 2022). "Although MALAT1 expression and role in cancer are widely described in the literature, the mechanisms regulating its activity are not well known." (PMID 35016717, 2022). "MALAT1 plays a critical role in tumorigenesis and progression of some cancers and has been considered a potential target in CRPC treatment." (PMID 35557985, 2022). "We have found that the expression level of MALAT1 in cancer tissues is significantly higher than that in normal tissues and is associated to the presence of both lymph node and distant metastases and low grade of differentiation." (PMID 35016717, 2022). "MALAT1 expression is enhanced in many cancer tissues, and MALAT1 is involved in the proliferation, apoptosis, migration, invasion, and spread of cancer cell metastasis." (PMID 36232884, 2022). "MALAT1 is overexpressed in many types of cancer, including CRCs, metastatic lung cancers, advanced stages of pancreatic cancers." (PMID 35922756, 2022). "Taken together, our research suggests that MALAT1 controls cancer glucose metabolism and progression by upregulating MYBL2-mTOR axis." (PMID 35557985, 2022). "Some lncRNAs have been thoroughly studied, like H19, Metastasis associated lung adenocarcinoma transcript 1 (MALAT1), or HOX transcript antisense intergenic RNA (HOTAIR), are considered to be pan-cancer markers involving multiple diverse malignancy tissues." (PMID 35697671, 2022).